EGFR (epidermal growth factor receptor)
Diseases named in the same sentence as EGFR in open-access papers (continued):
Sharing a sentence is not in itself a finding about the gene and the disease.
cancer (continued). "In contrast, in A549 cells, impairment of BRG1 function due to mutation of the BRD impairs its function and leads to its downregulation, resulting in EGFR governing the survival of cancer cells." (PMID 41514577, 2025). "Analyses of large-scale cancer dependency datasets demonstrate preferential strong EGFR dependency in ESCC." (PMID 40615716, 2025). "In summary, targeting the EGFR tyrosine kinase domain remains a promising strategy in the battle against cancer, particularly through the development of thiazole-based hybrid molecules." (PMID 41488515, 2025). "Although anti-EGFR therapies and chemotherapy are effective against mCRC, the potential for cancer cells to develop drug resistance limits their practical applicability." (PMID 39823981, 2025). "The goal of the current minireview was to highlight the significance of the mechanistic insights between the PTEN and PAFR as well as the PAFR and EGFR pathways in impacting cancer growth and/or efficacy of therapeutic agents in experimental model systems." (PMID 40160442, 2025). "It has been demonstrated that EGCG functions as a natural TKI by preventing wild-type EGFR from activating both in vitro and in vivo, which hinders the growth and survival of cancer cells." (PMID 40161336, 2025). "The identified signaling axis is applicable to all cancers harboring EGFR that deserve intensive investigations." (PMID 39781456, 2025). "Good results were generated by IR700, conjugated to specific mAbs targeting the EGFR molecule on the cancer cell surface and followed by the administration of NIR radiation." (PMID 40574027, 2025). "In this work, we used compound III as a lead compound to design a new cancer agent with dual activity against EGFR and CA." (PMID 40906750, 2025). "This study investigates the potential of CAR-engineered peripheral blood mononuclear cells (PBMCs) as a novel adoptive cell therapy against EGFR-positive cancers." (PMID 40002679, 2025). "In conclusion, compound 14 is a promising dual inhibitor targeting EGFR and human carbonic anhydrases hCA_IX and hCA_XII, demonstrating potent anti-cancer activity and a favorable safety profile." (PMID 40906750, 2025). "Collectively, the findings from the literature indicate that Methyl rosmarinate affects several pathways that are often dysregulated in cancer, including EGFR/PI3K/AKT/mTOR and MAPK/ERK, as well as the angiogenesis process." (PMID 40136434, 2025). "To define the appropriate CTC identification gate for our study, we examined the expression of these markers on several cancer cell lines: NCI-H1975 (with EGFRL858R mutation), A549 cells (with wild-type EGFR), and MCF-7 cells (low expression of EGFR)." (PMID 41439947, 2025). "These compounds suppress self-renewal capacity, inhibit cell proliferation via activation of the intrinsic apoptotic pathway, and downregulate the CypA/CD147 axis as well as EGFR signaling in NSCLC cancer stem cells (CSCs)." (PMID 41479915, 2025). "More importantly, the downregulation of EGFR expression levels in cancer cells correspondingly decreases the fluorescence intensity of Cy3‐AptEGFR@BPNSs, facilitating real‐time monitoring of EGFR dynamics." (PMID 40368641, 2025). "The current computational investigation focused on identifying small molecule inhibitors targeting EGFR which is a pivotal protein in cancer progression." (PMID 40344575, 2025).
cancer (continued). "GNPs conjugated with anti-epidermal growth factor receptor (GNPs-EGFR) monoclonal antibodies selectively bind to cancer cells with elevated EGFR expression." (PMID 40095737, 2025). "The emergence of resistant mutants in EGFR is considered to be the reason for the ineffectiveness of drugs, some of which have even been officially approved for cancer treatment." (PMID 40700134, 2025). "This study aimed to evaluate and summarize the best available evidence on the management of epidermal growth factor receptor inhibitor-induced skin toxicity symptoms in cancer patients, serving as a reference for medical staff." (PMID 41377804, 2025). "These proteins are involved in regulating key signaling proteins and pathways that are often dysregulated in cancer, such as EGFR, PI3K/AKT, c-Met, and the Wnt pathway." (PMID 40378957, 2025). "Previous studies indicated that epidermal growth factor (EGF) receptor (EGFR) induces GEFs to activate ARF6 in invasive cancers, which promotes cancer cell migration and invasion." (PMID 40082743, 2025). "The sensor’s ability to detect EGFR with high precision and its potential for real sample analysis demonstrate its value as a tool for early diagnosis and monitoring of EGFR-related cancers." (PMID 41440247, 2025). "EGFR is one of the most promising and appealing clinical and scientific targets in cancer therapy, and EGFR-targeted therapy is considered to be a potential anticancer treatment strategy." (PMID 40535810, 2025). "The crosstalk between EGFR and Src enhances cancer cell proliferation, survival, and metastasis, while also contributing to resistance against EGFR-targeted therapies." (PMID 39578555, 2025). "One potential mechanism underlying the histological transition from EGFR-mutant NSCLC to SCLC is lineage plasticity, which enables the dedifferentiation of cancer cells from an epithelial to a neuroendocrine lineage in response to EGFR-TKI treatment." (PMID 40248195, 2025). "These included MicroRNAs in cancer, ErbB signaling pathway, PI3K-Akt signaling pathway, EGFR tyrosine kinase inhibitor resistance, and chemical carcinogenesis—receptor activation." (PMID 41462933, 2025). "Elevated EGFR levels can increase receptor signalling, promote malignant transformation, provide cancer cells with survival benefits, and foster drug resistance." (PMID 39910656, 2025). "With continuous in-depth research on EGFR, TCMs that target EGFR will have greater potential for utilization in cancer treatment." (PMID 40535810, 2025). "This co-treatment led to a marked decrease in EGFR expression and reduced cancer cell proliferation." (PMID 40124344, 2025). "Aberrant activation of the EGFR pathway contributes to the process of tumorigenesis and cancer progression." (PMID 40002679, 2025). "Oncogenic alterations, such as mutations in EGFR and KRAS, along with their downstream signaling pathways, give unique characteristics to cancer cells that shape the TME/TIME." (PMID 40524071, 2025). "The activation of EGFR triggers the NF-κB pathway, thereby conferring survival advantages to cancer cells through the upregulation of anti-apoptotic genes." (PMID 39931370, 2025). "For example, the profile of the Bruton’s tyrosine kinase (BTK) inhibitor ibrutinib in the Oncolines® cancer cell line panel shows similarity with that of epidermal growth factor receptor (EGFR) tyrosine kinase inhibitors." (PMID 41199836, 2025). "TKIs are a class of drugs that target EGFR, inhibiting its tyrosine kinase activity to prevent cancer cell proliferation." (PMID 40084262, 2025). "The most enriched pathways included those associated with cancer, proteoglycans in cancer, TNF signaling, PI3K-Akt signaling, and resistance to EGFR tyrosine kinase inhibitors." (PMID 40259353, 2025). "Mounting evidence has established the critical role of EGFR–Akt signaling in promoting cancer cell invasion and migration." (PMID 40082743, 2025).
cancer (continued). "Examples of such systems include nanobodies–liposomes, nanobodies–micelles, and nanobody–albumin nanoparticles with increased specificity for EGFR-expressing cancer cells." (PMID 41009364, 2025). "Next, EGFR is also a famous receptor involved in cancer cell survival, proliferation, and migration and metastasis." (PMID 40868982, 2025). "The complete inhibition of EGF-mediated phosphorylation of the WT indicates the non-specific effect of erlotinib on normal tissues in which wild-type EGFR is expressed when applied in cancer patients." (PMID 40649937, 2025). "More importantly, our research demonstrates that the reduction in EGFR expression levels within cancer cells corresponds to a proportional decline in fluorescence intensity, thereby facilitating precise tracking of EGFR dynamics." (PMID 40368641, 2025). "These signaling pathways have been identified as promoting tumor growth, survival, and resistance to cell death, thereby providing further evidence to support the role of the EGFR as a critical driver of cancer progression." (PMID 40006082, 2025). "The binder showed strong, calcium-dependent binding to the recombinant extracellular domain of EGFR and specificity for EGFR-expressing cancer cells." (PMID 41289384, 2025). "Epidermal growth factor receptor (EGFR) is frequently overexpressed in different cancers, and its expression level is positively correlated with cancer progression and poor prognosis." (PMID 40527884, 2025). "Combines targeted therapy (Gefitinib), gene therapy (YAP-siRNA), and photodynamic therapy (PDT) to overcome EGFR-TKI resistance in cancer." (PMID 40235732, 2025). "In normal cells, the number of EGFR is estimated to be around 40,000–100,000 receptors per cell, whereas in cancer cells this number rises to more than 106 receptors per cell." (PMID 39940134, 2025). "Conjugating the anti-EGFR monoclonal antibody nimotuzumab with 27 nm Au NP significantly enhanced therapeutic efficacy against EGFR-overexpressing cancers, as evidenced by lower IC50 values compared to free nimotuzumab." (PMID 40124344, 2025). "Further investigation revealed that there were different correlations of Hub-EGFR.Sig with MSI across different cancer types." (PMID 40574864, 2025). "EGFR signaling is one of the proliferation mechanisms that is widely studied in various cancers including TNBC." (PMID 39942711, 2025). "EGFR belongs to the ErbB family of receptor tyrosine kinase (RTK), and is the most frequently mutated gene in human cancers." (PMID 40859900, 2025). "Epidermal growth factor receptor (EGFR) is frequently overexpressed in various cancer cells and has been reported to contribute to radioresistance." (PMID 40565174, 2025). "These works showed that EGFR glycosylation and phosphorylation coregulated the development of two different cancer types." (PMID 40154885, 2025). "In certain pathological conditions, such as cancer, this balance is disrupted, resulting in increased stability of the EGFR protein and enhanced localization to the cell membrane." (PMID 40877231, 2025). "For example, mutations disrupting the glycine zipper motif in PTPRJ reduce its oligomerisation, which in turn enhances phosphatase activity and suppresses EGFR-driven cancer phenotypes." (PMID 40941028, 2025). "The epidermal growth factor receptor (EGFR) is one of the critical RTKs that is involved in cancer cell proliferation, migration, and survival." (PMID 39948411, 2025). "In contrast, TNS4 acts predominantly as an oncoprotein across carcinomas by stabilizing epidermal growth factor receptor (EGFR), driving epithelial–mesenchymal transition and invasion, and sustaining proliferation." (PMID 40906372, 2025). "Overactive epidermal growth factor receptor (EGFR) signaling is often involved in driving different types of carcinomas." (PMID 41262582, 2025).
cancer (continued). "In carcinoma cells, integrin can trigger signal transmission from the EGFR through both ligand-dependent and ligand-independent pathways." (PMID 40362195, 2025). "The epidermal growth factor receptor (EGFR) is involved in the development and growth of various types of malignant carcinomas." (PMID 40508013, 2025). "In various cancers, an association between signal transducer and activator of transcription 3 (STAT3), interleukin 6 (IL6), and epidermal growth factor receptor (EGFR) on PD-L1 expression has been shown in varying degrees." (PMID 38434518, 2024). "This reflects the tissue specificity of CNAs in cancer and is most likely due to the presence of key oncogenes in solid tumours (EGFR, MET and BRAF), and well-known tumour suppressor genes in blood cancers (CUX1 and IKZF1)." (PMID 38999925, 2024). "In KEGG enrichment analysis of toxic targets, the top 20 significant pathways of six key SOCs were similar, mainly including EGFR tyrosine kinase inhibitor resistance, pathway in cancer, PI3K-Akt signaling pathway, etc." (PMID 39193326, 2024). "It was observed that PIK3CA was also associated with EGFR, this implies that E. acoroides Extract is also involved in pathways such as PI3K/AKT and HIF-1Alpha signaling which were recognized as cancer makers." (PMID 38474594, 2024). "It was inferred that saporin accumulated at high concentrations in cancer cells with high expression of EGFR, and saporin exerted its enzymatic activity only in specific wavelength to NPe6-irradiated cells in this approach." (PMID 38790935, 2024). "EGFR is a pivotal protein receptor in cancer, engaged in signaling pathways that oversee cell growth, division, and survival." (PMID 38474160, 2024). "The CTCs have variable expression for the epithelial and cancer-specific markers, such as EpCAM, EGFR, E-cadherin, mammaglobin, HER2, ER, and AR." (PMID 39594700, 2024). "Its expression positively correlates with cancer progression and poor prognosis, which led to the development of numerous EGFR inhibitors, such as afatinib, brigatinib, or vandetanib." (PMID 38339275, 2024). "Growth factor receptors like EGFR and ion channels often functionally cooperate in cancer cells so that anti-cancer effects of TKIs can be potentiated by co-treatment with ion channel modulators." (PMID 38177097, 2024). "Gefitinib, an EGFR inhibitor, has been shown to induce dose‐dependent growth arrest in cancer cells." (PMID 39415846, 2024). "Cancer cells are known to develop resistance to EGFR TKIs after prolonged exposure, with over half of TKI-resistant cases able to be attributed to the EGFR-T790M mutation." (PMID 38398217, 2024). "HIF upregulation results in transcriptional activation of several cancer-driving genes, including epidermal growth factor receptor (EGFR)." (PMID 38390862, 2024). "Amphiregulin (AREG) is a member of the epidermal growth factor (EGF) family, which activates the EGF receptor (EGFR), influencing multiple tumorigenic characteristics of cancers." (PMID 39452130, 2024). "Many agents have been identified as EGFR inhibitors, and some of them have been chemotherapeutically approved against various cancer types." (PMID 39065774, 2024). "As a result, cancer therapies that target EGFR, using drugs that directly bind to the receptor, have been extensively used in clinical treatments for EGFR-positive NSCLC, and their strong efficacy has been well-established." (PMID 39897079, 2024). "EREG serves as a ligand of the epidermal growth factor receptor (EGFR) and its deregulation in different types of cancer leads to activation of EGFR signaling pathways and tumorigenesis." (PMID 38016355, 2024). "By binding to the EGFR expressed in cancer cells, cetuximab blocks the ligand binding site, preventing receptor dimerization and downstream activation." (PMID 39791733, 2024).
cancer (continued). "Triple targeting of ALOX5, COX-2 and double mutant EGFR by novel quinazolinone tethered phenyl urea derivatives demonstrate anti-inflammatory and anti-cancer activities in numerous cancer cell lines, not limited to BT-459 breast cancer cell line." (PMID 38612771, 2024). "For example, bispecific antibodies targeting EGFR and receptor tyrosine kinases (RTKs) have shown better clinical therapeutic effects than monospecific antibodies in cancer treatment." (PMID 39594573, 2024). "Remaining drug-tolerant persistent (DTP) cancer cells limit the efficacy of targeted therapy in EGFR, ALK and KRAS mutant non-small cell lung cancer (NSCLC)." (PMID 38702301, 2024). "These drugs work by inhibiting the activation of the epidermal growth factor receptor, a cell surface receptor that is essential for cancer cell growth and survival." (PMID 38655092, 2024). "Cetuximab’s has found effective in EGFR over expressing cancer cells, which is conjugated TH (THC3) with intercalated doxorubicin (DOX) medication, or THDC3, demonstrated preferential death of MDA-MB-468 cancer cells." (PMID 39720730, 2024). "Among them, the aptamer CL-4RNV616 specifically targets the epidermal growth factor receptor (EGFR), which is highly expressed in many cancers and is considered a prognostic indicator of cancer." (PMID 38305844, 2024). "EGFR and BAK1 were the most prevalent genes common between ancestries, and they were shown to be linked to several types of cancers." (PMID 38398891, 2024). "Migration of A2780 cancer cells into matrigel depends on EGFR, since it is abolished after EGFR knock-down using siRNA." (PMID 39594667, 2024). "The results showed that the targets were mainly enriched in HIF-1 signaling pathway, VEGF signaling pathway, Central carbon metabolism in cancer, EGFR tyrosine kinase inhibitor resistance." (PMID 39502531, 2024). "Patients with stage IV NSQ cancer had the worst survival outcomes compared with other stages across EGFR-positive, ALK-positive, and WT subgroups (P < .001)." (PMID 38334998, 2024). "Ligand binding to EGFR can activate downstream signaling pathways that promote cell proliferation and survival, contributing to cancer progression." (PMID 39457373, 2024). "In fact, many EGFR tyrosine kinase inhibitors (EGFR-TKIs) have been approved for the treatment of cancers, showing good anti-cancer effect." (PMID 39193326, 2024). "In the context of EGFR, CRISPR-Cas9 can be programmed to target and modify the mutated sequences responsible for cancer growth, potentially inhibiting tumor progression and improving patient outcomes." (PMID 38195537, 2024). "It has been reported that some patients with cancer who are treated with EGFR inhibitors develop invasive aspergillosis (12, –, 15)." (PMID 39475281, 2024). "In our case, anti-CK (+), anti-P40 (+), anti-CK5/6 (+), anti-Ki67 (+, hot spot area 80%) and anti-EGFR (++++) in cancer cells were high positive, and complete pathological remission was achieved after receiving ICIs treatment." (PMID 39076983, 2024). "This nanopharmaceutical serves as a theranostic nanoplatform for EGFR-overexpressing cancers, including TNBCs (triple-negative breast cancer)." (PMID 38341580, 2024). "The IRDye800 conjugated with the clinically approved monoclonal antibody anti-epidermal growth factor EGFR Cetuximab (cetuximab-IRDye800) has shown promising results as a specific tracker in other cancer types (i.e., brain, pancreas, head, and neck)." (PMID 39218855, 2024). "M6A‐related genes such as BRD4, MYC, SOCS2, and EGFR are frequently involved in the progression of cancers including LUAD." (PMID 39323079, 2024). "Amongst them, 33 (25.2%) have been reported as GBM-related (e.g., EGFR, PTEN, MTOR) and 29 (22.1%) as cancer-associated genes (e.g., AGAP2, SOX2)." (PMID 38724522, 2024).